PTH (parathyroid hormone)
Diseases named in the same sentence as PTH in open-access papers (continued):
Sharing a sentence is not in itself a finding about the gene and the disease.
Hypocalcemia (continued). "However, many PTH criteria have been proposed by previous authors to predict which patients are at risk of developing clinically relevant postoperative hypocalcemia." (PMID 22399155, 2012). "In addition, in the relationship between Ca2+ and bone metabolism, PTH secretion is increased due to Ca2+ deficiency-induced hypocalcemia, and serum Ca2+ level is rapidly restored by PTH stimulating osteoclasts in the bone." (PMID 22837661, 2012). "Single i-PTH testing done 12 hours after total thyroidectomy may be used as a screening test to detect patients at risk for symptomatic hypocalcemia." (PMID 23108824, 2012). "In addition, it has been reported that the use of intraoperative parathyroid hormone (IOPTH) monitoring during parathyroid surgery can accurately predict patients at risk of developing postoperative hypocalcemia." (PMID 21197072, 2010). "The hypocalcaemia induced by the infusion of EDTA caused a transient increase in plasma intact PTH from a baseline value of 27 ± 16 ng/l to a peak value of 98 ± 38 ng/l after the end of the 30 min infusion (at 33 min), with subsequent rapid decrease near to the baseline values." (PMID 19578490, 2008). "PTH levels (determined 6 hours after total thyroidectomy) could be effective for early prediction of the risk of postsurgical hypocalcemia and IV calcium requirements during hospitalization, comparing it with the predictive capacity of serum calcium levels at 24 and 48 hours after surgery." (PMID 40671592, 2026). "Additionally, to mitigate the risk of postoperative hypocalcemia, preoperative vitamin D supplementation to normal levels can enhance the compensatory capacity in order to maintain calcium homeostasis following sudden decreases in PTH levels after RFA." (PMID 40244409, 2025). "Moreover, there may be sex-related differences in the effects of steroid hormones on secretion of PTH and genetic variations in cell signaling pathways, resulting in greater susceptibility to hypocalcemia in female patients." (PMID 40786097, 2025). "On the contrary, calcimimetic agents, such as cinacalcet and etelcalcetide, which increase the sensitivity of the calcium-sensing receptor to extracellular calcium and decrease PTH secretion, may cause hypocalcemia, leading to an increased risk of arrhythmia and heart failure." (PMID 40045219, 2025). "Further workup revealed hypocalcemia (total calcium of 6.8 mg/dL, ionized calcium of 0.91 mmol/L), severe vitamin D deficiency (25-hydroxyvitamin D of 3.5 ng/mL), low phosphate, elevated alkaline phosphatase, and a high serum parathyroid hormone level, all indicative of nutritional rickets." (PMID 41552144, 2025). "Therefore, prolonged treatment with cinacalcet can inhibit parathyroid cell proliferation and lower serum PTH levels, which may significantly increase the risk of hypocalcemia in susceptible patients." (PMID 41144478, 2025). "Thus, deficiency of vitamin D3 could predominantly produce hypocalcemia as approved by the current study, which thus stimulates the proliferation of PTH." (PMID 40231299, 2025). "Other factors that may exacerbate risk of hypophosphatemia and hypocalcemia should be considered when monitoring electrolytes with measurement and supplementation of 25-OH-Vitamin D and magnesium (due to impaired PTH secretion in the presence of hypomagnesemia) if deficient." (PMID 41445550, 2025). "Multivariable logistic regression analysis results had revealed that high baseline PTH (OR: 1.003, 95% CI: 1.001–1.005, p < 0.001) and low baseline total cholesterol (OR: 0.987, 95% CI: 0.979–0.995, p = 0.002) were independently associated with postoperative hypocalcemia." (PMID 40731865, 2025). "Optimizing preoperative protocols to adjust Ca, PTH, and 1,25(OH)2D levels to improve the management of patients undergoing total thyroidectomy and to prevent extreme intraoperative PTH decreases may reduce the risk of hypocalcemia." (PMID 38803480, 2024).
Hypocalcemia (continued). "Consequently, a lack of magnesium may result in disruption to the calcium/phosphate homestays regulated by active vitamin D/PTH and may cause vitamin D–resistant hypocalcemia." (PMID 37007781, 2023). "Therefore, denosumab strongly inhibits bone resorption, resulting in an increase in calcium release from the bones, causing hypocalcemia, followed by effects on the parathyroid gland, which is the reason for the increased serum PTH level and decreased serum phosphate level." (PMID 35140619, 2022). "Therefore, inactivating GNAS pathogenic variants from maternal allele leads to a dramatic reduction in Gsα expression, characterized by end-organ resistance to multiple hormones, primarily PTH and TSH, causing hypocalcemia, hyperphosphatemia, elevated PTH levels and hypothyroidism." (PMID 35871092, 2022). "Additionally, when the amount of diet-derived Ca received by laying hens is insufficient for eggshell formation and high egg production, Ca deficiency-induced hypocalcemia could further stimulate PTH production." (PMID 34827866, 2021). "Moreover, the routine use of PTH for the early identification of hypocalcemia may help reduce the length of hospitalization and associated costs, though further research will be required." (PMID 34574074, 2021). "Therefore, we hypothesized that PTH relative decline (RDP) may contribute to identifying high-risk patients of hypocalcemia who need calcitriol supplement after thyroidectomy." (PMID 33762946, 2021). "The similar clinical presentation between familial isolated hypoparathyroidism in humans and equine idiopathic hypocalcemia led to the hypothesis that a coding variant within PTH, GCM2, CASR, GNA11 or TRPM6 would be associated with idiopathic hypocalcemia of TB foals." (PMID 32986719, 2020). "However, it is thought that hypocalcemia and/or low PTH levels could cause several clinical issues by inducing oxidative stress." (PMID 33033457, 2020). "Also, the common causes of hypocalcemia are PTH related, or vitamin D described." (PMID 33015068, 2020). "A case of severe symptomatic hypocalcemia related to Nilotinib was also reported, with an immune-mediated destruction of the parathyroid glands or a drug interference with calcium sensing receptors (CaSRs) and ensuing insufficient PTH secretion being the suggested pathogenic mechanisms." (PMID 32509580, 2020). "Hypocalcemia may be associated with imbalanced VD and PTH in the acute phase of COVID-19." (PMID 32589164, 2020). "Hypocalcemia may be associated with imbalanced VD and PTH levels." (PMID 32589164, 2020). "In addition, in the same group of patients altered bone and mineral homeostasis (as indicated by hypocalcemia, hyperphosphatemia, vitamin D deficiency and altered parathyroid hormone activity) was identified with high frequency of pain and fractures in 12.5% of patients (submitted for publication)." (PMID 31360455, 2019). "The causes of hypocalcemia in premature infants include early discontinuation of calcium transfer through the placenta, an exaggerated decrease in the serum calcium level that physiologically occurs postpartumly, the reduced response of target organs to PTH, and increased calcitonin levels." (PMID 31320908, 2019). "However, we suggest that patients with levels of intact PTH progressively rising or persistently above the upper normal limit for the assay be evaluated for modifiable factors, including hyperphosphataemia, hypocalcaemia, high phosphate intake, and vitamin D deficiency (2C)." (PMID 30236082, 2018). "However, we suggest that patients with levels of intact PTH progressively rising or persistently above the upper normal limit for the assay be evaluated for modifiable factors, including hyperphosphatemia, hypocalcemia, high phosphate intake, and vitamin D deficiency” (2C)." (PMID 29912988, 2018).
Hypocalcemia (continued). "ADH is associated with hypocalcemia, hyperphosphatemia, hypomagnesemia, and inappropriately low or normal PTH concentrations; some patients may also be hypercalciuric or develop a Bartter-like syndrome characterized by hypokalemic alkalosis, renal salt wasting, and hyperreninemic hyperaldosteronism." (PMID 28194447, 2017). "This is relevant because PTH could be elevated in states of vitamin D deficiency and hypocalcemia." (PMID 25548555, 2014). "Although some studies have suggested that low preoperative 25-hydroxyvitamin D (25-OHD) levels may increase the risk of hypocalcemia and decrease the accuracy of single quick parathyroid hormone in predicting hypocalcemia after total thyroidectomy, the literature remains scarce and inconsistent." (PMID 22968355, 2013). "Laboratory evaluation demonstrated hypocalcemia (8.5 mg/dL), hyperphosphatemia (8.4 mg/dL), and a markedly elevated parathyroid hormone (PTH) level of 1695.8 pg/mL." (PMID 41362862, 2026). "Clinical manifestations typically result from hypocalcemia and resemble those seen in hypoparathyroidism, while laboratory tests show elevated serum PTH levels along with hypocalcemia and hyperphosphatemia." (PMID 41884215, 2026). "This case, together with the literature, underscores the need for extended follow-up in patients presenting with hypocalcemia and blunted PTH responses after COVID-19." (PMID 42267299, 2026). "Conversely, those with hypoparathyroidism showed low PTH levels (22.2 pg/mL) despite significant hypocalcemia." (PMID 41704483, 2026). "The rapid surge in PTH was likely a compensatory response to hypocalcemia, reflecting the body's immediate attempt to maintain calcium homeostasis." (PMID 40663633, 2026). "Hypocalcemia is common in Coronavirus Disease 2019 (COVID-19), yet the insufficient compensatory rise in parathyroid hormone (PTH) and its long-term outcomes remain poorly characterized." (PMID 42267299, 2026). "Biochemical tests revealed consistent abnormalities in both subjects, including hypocalcemia, hyperphosphatemia, and elevated levels of PTH and thyroid-stimulating hormone (TSH)." (PMID 42238246, 2026). "Laboratory results indicated severe hypocalcemia, hyperphosphatemia, and low parathyroid hormone levels, supporting a link between endocrine dysregulation and disease severity in Fahr’s syndrome patients." (PMID 41403967, 2026). "Antiepileptic drugs (AEDs) accelerate cytochrome P450-mediated vitamin D catabolism, leading to hypocalcemia and a compensatory rise in parathyroid hormone (PTH) levels, which subsequently enhances osteoclast activity and bone resorption." (PMID 41596293, 2026). "Hypoparathyroidism (HypoPT) is a rare endocrine disorder characterized by insufficient parathyroid hormone (PTH) levels, leading to hypocalcemia and hyperphosphatemia." (PMID 41675830, 2026). "Idiopathic hypoparathyroidism is a rare endocrine disorder characterized by impaired parathyroid hormone (PTH) secretion leading to hypocalcemia and hyperphosphatemia." (PMID 41769609, 2026). "Laboratory evaluation revealed severe hypocalcemia, hypomagnesemia, and markedly reduced parathyroid hormone levels, consistent with hypoparathyroidism." (PMID 42016627, 2026). "Laboratory tests showed leukocytosis with neutrophilic predominance, hypokalemia, hypocalcemia, hyperphosphatemia, and elevated PTH." (PMID 42294472, 2026). "Laboratory testing revealed significant hypocalcemia, hypomagnesemia, and low intact parathyroid hormone levels, which were consistent with functional hypoparathyroidism." (PMID 41668966, 2026). "The coexistence of hypocalcaemia, hyperphosphatemia, and suppressed PTH levels is indicative of primary hypoparathyroidism, which, in the absence of identifiable secondary causes, suggests a potential direct role of HIV in the glandular dysfunction." (PMID 41295288, 2025).
Hypocalcemia (continued). "Biochemical hallmarks include hypokalemia (mean 3.02 mmol/L), hypocalcemia (mean 1.57 mmol/L), elevated PTH (mean 369.2 pg/mL), hyperphosphatemia (60%), hypomagnesemia (30%), and vitamin D deficiency (40%)." (PMID 40893942, 2025). "BMD originates from reduced 1,25-dihydroxy vitamin D and hypocalcemia, which lead to secondary hyperparathyroidism, with increased parathyroid hormone (PTH) levels and hyperphosphatemia as the kidney damage progresses." (PMID 40045219, 2025). "High levels of alkaline phosphatase are identified as a predictor of calcium and PTH decline that correlates with postoperative hypocalcemia." (PMID 39941666, 2025). "Our patient had a low-normal PTH level despite significant hypocalcemia, indicating an inadequate parathyroid response." (PMID 40717880, 2025). "Laboratory indicators of PHP include hypocalcemia, hyperphosphatemia, and elevated or inappropriately high PTH concentration." (PMID 40444234, 2025). "The average age of diagnosis for PHP1A is around seven years when PTH resistance and hypocalcemia become apparent." (PMID 40125101, 2025). "Regarding postoperative hypocalcemia, our analysis identified high baseline PTH levels and low total cholesterol as independent predictors." (PMID 40731865, 2025). "All patients exhibited the characteristic biochemical profile of PHP1B: severe hypocalcemia (mean serum calcium: 1.55 mmol/L), hypokalemia (mean serum potassium: 3.14 mmol/L), and elevated PTH (mean PTH: 422.1 pg/mL)." (PMID 40893942, 2025). "Peptides provide an effective therapy for hypoparathyroidism, with PTH replacement offering a superior physiologic treatment compared to conventional therapy with active vitamin D and calcium, which address hypocalcemia but fail to restore normal PTH function." (PMID 40143070, 2025). "This patient also presented with biochemical features of PTH resistance, including hypocalcemia and significantly elevated iPTH (247.4 pg/mL)." (PMID 41155848, 2025). "Hypocalcemia then stimulates the production of PTH, which induces bone turnover to increase serum calcium and contribute to arterial calcification." (PMID 41233702, 2025). "Hypomagnesemia can impair PTH secretion and action, leading to secondary hyperparathyroidism (sHPT) and hypocalcaemia." (PMID 41295288, 2025). "Literature indicates that a decrease in PTH levels within the first 24 hours, particularly among asymptomatic women, correlates with a sensitivity exceeding 61% in predicting hypocalcemia." (PMID 40091995, 2025). "Hypoparathyroidism (HypoPT) is a rare endocrine disorder characterized by low parathyroid hormone (PTH) levels, hypocalcemia, hyperphosphatemia, reduced active vitamin D (1,25-OH2 vitamin D), and hypercalciuria." (PMID 40794165, 2025). "Laboratory tests revealed hypocalcaemia (1.8 mmol/L; norm: 2.2–2.6), but parathyroid hormone levels were normal (3.3 pmol/L; norm: 1.6–6.9)." (PMID 41473459, 2025). "In patients with hypocalcemia, it is essential to evaluate serum albumin, phosphorus, magnesium, 25(OH) vitamin D, and particularly PTH levels." (PMID 40717880, 2025). "Regarding specificity, the reduction in PTH values reached a level of 87% in predicting hypocalcemia, while a reduction of up to 98% showed 98.6% specificity in determining the need for exogenous calcium supplementation." (PMID 40091995, 2025). "In our study, we also identified high level of preoperative PTH and ALP, and low level of preoperative serum calcium as risk factors for severe hypocalcemia." (PMID 41367906, 2025). "In the case of low serum PTH or symptoms of hypocalcaemia, subsequent measurements of ionized or albumin-adjusted serum calcium are needed in the postoperative interval (days–weeks) to assess any need for or guide treatment of hypoparathyroidism." (PMID 41229353, 2025). "Laboratory investigations demonstrated chronic hypocalcaemia with suppressed parathyroid hormone and hyperphosphataemia." (PMID 41631225, 2025).
Hypocalcemia (continued). "Laboratory investigations revealed severe hypocalcemia (serum calcium 4.5 mg/dL), low vitamin D, and inappropriately low-normal parathyroid hormone (PTH) levels." (PMID 40717880, 2025). "Both patients had besides hypocalcemia, hyperphosphatemia and elevated PTH levels of 76.4 pmol/L (nl 1.6-7.2) and 36.5 ng/L (nl 1.1-6.9), respectively." (PMID 40904804, 2025). "This disorder is characterized by lifelong hypocalcemia, hypomagnesemia, hyperphosphatemia, low or inappropriately normal PTH concentrations, and inappropriately normal or increased urinary calcium excretion." (PMID 40086735, 2025). "When the body's response to PTH is impaired, it disrupts calcium homeostasis, leading to hypocalcemia, hyperphosphatemia, and potential skeletal abnormalities." (PMID 40125101, 2025). "The possible reason is the rapid reduction in PTH levels shifts the bone turnover equilibrium toward mineralization, resulting in massive calcium influx into osteoid tissue and subsequent hypocalcemia." (PMID 40979702, 2025). "A constant concentration of calcium is essential for various biological functions; therefore, in cases of hypocalcemia, there is an increased release of parathyroid hormone, leading to enhanced calcium reabsorption and the production of calcitriol." (PMID 39941180, 2025). "Post EDTA-induced hypocalcaemia, maximal PTH response remained significantly lower in the HIV-positive group compared to the control group (p < 0.04), suggesting impaired parathyroid function in AIDS." (PMID 41295288, 2025). "Based on our results, the PTH value of 40 pg/mL is able to distinguish individuals with SHPT characterized by hypersecretion of PTH, hypovitaminosis D and hypocalcemia." (PMID 41301518, 2025). "Blood parathyroid hormone increased, Peripheral arterial occlusive disease, Hypocalcemia, Shunt aneurysm, and Shunt infection occured predominantly in males and has a stronger signal intensity than females." (PMID 40170738, 2025). "The literature suggests that measuring PTH in the immediate postoperative period can predict hypocalcemia and guide calcium supplementation, potentially reducing hospital stays and complications." (PMID 40091995, 2025). "Laboratory re-evaluation confirmed PHP1A with findings of hypocalcemia, hyperphosphatemia, and elevated PTH levels, alongside normal magnesium levels." (PMID 40125101, 2025). "Two patients were refractory to treatment and had an inadequate parathyroid response (low or normal PTH levels with hypocalcemia), which led to the suspicion of hypomagnesemia, as hypomagnesemia can blunt the parathyroid response." (PMID 41142805, 2025). "Our data showed that preoperative parathyroid hormone and alkaline phosphatase were significantly higher in patients who developed hypocalcemia." (PMID 40517023, 2025). "The definitions of hypoparathyroidism included reduced PTH levels only, hypocalcaemia only, or a combination of both." (PMID 41229353, 2025). "Laboratory findings showed marked hypocalcemia, low parathyroid hormone levels, and borderline elevated phosphate." (PMID 41018325, 2025). "ADH1 patients are biochemically characterized by hypocalcemia with inappropriately low but detectable or normal PTH levels, high normal or elevated phosphate, and normal or low levels of magnesium." (PMID 39607645, 2025). "Biochemical profiling revealed hypokalemia (mean potassium 3.14 mmol/L), hypocalcemia (mean calcium 1.55 mmol/L), and elevated PTH (mean 422.1 pg/mL)." (PMID 40893942, 2025). "This retrospective comparative analysis demonstrates that the intraoperative topical application of papaverine effectively reduces the occurrence of hypocalcemia and early HP after total thyroidectomy, while also aiding quicker PTH recovery." (PMID 41356014, 2025). "Low levels of 25(OH)D3 can lead to muscle weakness, which can be mistakenly considered a symptom of hypocalcemia, and some tissues can generate 1,25(OH)2D3 from 25(OH)D3 independently of PTH." (PMID 39607645, 2025).